KRAS (KRas proto-oncogene, GTPase)
Diseases named in the same sentence as KRAS in open-access papers (continued):
Sharing a sentence is not in itself a finding about the gene and the disease.
tumor (continued). "Mutations in the genes encoding the components of the MAPK pathway, such as KRAS, NRAS, and BRAF, are frequently observed in LGSOCs, driving uncontrolled cell proliferation and tumor development." (PMID 39409889, 2024). "The KRASG12C drug candidate, ARS-1620, demonstrated in vivo tumour growth inhibition for the first time, verifying the potential of KRAS-targeted therapy." (PMID 40391409, 2024). "Immunohistochemistry revealed that the tumour was microsatellite stable (MSS) and carried a mutation in KRAS." (PMID 39062841, 2024). "Combining FAK inhibition therapy can potentially restore the sensitivity of drug-resistant cells to MEK or KRAS inhibitors, improving their anti-tumor effect." (PMID 38410129, 2024). "Studies using xenograft models have demonstrated that Sotorasib can inhibit ERK phosphorylation and tumor cell growth in KRAS G12C-mutant cells, leading to durable tumor regression as a monotherapy." (PMID 39273605, 2024). "Another combination strategy was based on KRAS inhibition triggering pro-inflammatory changes in the tumor microenvironment." (PMID 38978742, 2024). "Some of the most common driver mutations found in sporadic CRC are activating mutations in KRAS accounting for 30–40% of all CRCs and activating mutations in BRAF which occur in 5–15 % of the tumours." (PMID 38040818, 2024). "Lox-Cre recombination conditionally removes a stop codon, resulting in KRAS LSLG12D/V alleles, which in turn promotes tumor initiation in these models." (PMID 39547513, 2024). "Amino acids act as pivotal signaling molecules, stimulating signal pathways like mTORC1, MYC and KRAS to drive tumor growth and proliferation." (PMID 38218942, 2024). "Oncogenic KRAS mutations are found in over 90% of PDAC cases and drive tumor initiation, progression, and maintenance." (PMID 39001498, 2024). "In contrast, KRAS G12D tumours, which exhibited a much stronger level of Protein kinase B (AKT) phosphorylation compared to those expressing KRAS WT or Q61H." (PMID 39372214, 2024). "In the training set, the cutoff values of tumor size and KRAS VAF for predicting positive rim enhancement were > 3.9 cm and > 17.22%; they had AUCs of 0.728 and 0.762, respectively." (PMID 38525415, 2024). "Combination chemotherapy using gemcitabine/(n)ab-paclitaxel (GnP) with MRTX1133, a KRAS G12D inhibitor, showed a significant reduction in relapse and longer tumor growth inhibition in both primary and metastatic settings." (PMID 39597944, 2024). "A 90-day treatment study in a series of KRAS(G12X) xenograft models demonstrated a marked and significant increase in time to tumour doubling from baseline compared with controls." (PMID 38589574, 2024). "Comprehensive analyses of miRNA expression profiles across various tumour types have been performed and compared with KRAS expression." (PMID 39057123, 2024). "On the contrary, KRAS-driven tumor cells have the ability to bypass the late G1 checkpoint of the cell cycle and are arrested in the S phase or G2/M phase due to deprivation of glutamine, which is solely responsible for this phenomenon mine." (PMID 38172980, 2024). "KRAS mutations occur in approximately 40% of CRC cases and are associated with advanced disease status, poor tumor differentiation, distant metastasis, and resistance to chemotherapy." (PMID 39683504, 2024).
tumor (continued). "KRAS signalling in monoclonal tumours showed a higher net enrichment score than found in minor clones but a lower one than for major clones." (PMID 39478206, 2024). "In the following years, retrospective analysis of RAS (KRAS, NRAS) and BRAF mutations in tumor tissue samples from patients included in these pivotal trials showed a greater benefit in patients with tumors not harboring RAS/BRAF mutations." (PMID 38711991, 2024). "When adjusting the model also by treatment status, performance status, and tumor stage, the HR for KRAS G12C was slightly lower (1.75, 95% CI 1.01–3.04) but still significant (p = 0.048)." (PMID 38785486, 2024). "In a study involving GMB tumor cells, it was demonstrated that the KRAS/ERK signaling pathway regulates the overexpression of CD44 in response to radiation by downregulating micro-RNA expression in GBM cells." (PMID 38672650, 2024). "Preclinically, RMC-7977 demonstrated potent activity against RAS-addicted tumours carrying various RAS genotypes, particularly against cancer models with KRAS codon 12 mutations (KRASG12X)." (PMID 38589574, 2024). "β-Elemene as a complementary drug in combination with cetuximab inhibites tumor growth and migration of KRAS mutant CRC cells by inducing ferroptosis." (PMID 38738174, 2024). "In KRAS mutation group, high P4HA2 expression is the only independent prognostic factor in tumor recurrence." (PMID 38522060, 2024). "CCL5 deficiency in KRAS mutant LUAD resulted in a decrease in Treg cells and reduced lung tumor burden, indicating that the production of CCL5 by tumor cells contributes to an immunosuppressive environment in the lung." (PMID 39114657, 2024). "Three mutations were detected in both tumor and plasma samples for the same female: EGFR p.E746_A750del (sample number 40), KRAS p.G12A (sample number 48), and EGFR p.L747_P753delins (sample number 50)." (PMID 38730722, 2024). "Gain-of-function screens of epigenetic regulators in KRAS-mutant PDAC models identified HDAC5 as a driver of resistance to KRAS inhibition within the tumor microenvironment." (PMID 38668053, 2024). "Amongst the identified cancer antigens of KRAS-mutated PDAC, CEA and MSLN were reported to be overexpressed and promoted tumor progression PDAC." (PMID 39453574, 2024). "Compared to clinically approved RAS–MAPK pathway inhibitors, NST-628 robustly and persistently reduces pathway reactivation in KRAS–G13D tumor models." (PMID 38791529, 2024). "Preclinical studies, including mouse models, have demonstrated that KRAS-G12V-specific TCR-T cells exhibit significant anti-tumor activity." (PMID 39439803, 2024). "Preclinical studies have shown that inhibiting SHP2 can suppress MAPK pathway activation and inhibit tumor growth dependent on RTK pathway activation and/or carrying oncogenic KRAS mutations." (PMID 39184861, 2024). "Hyperactivation of KRAS in almost all tumours drives RAC1 activation, conferring enhanced migratory and proliferative capacity as well as macropinocytosis." (PMID 38712822, 2024). "Consistent patterns were observed across other tumor types, with KRAS consistently identified as the most differential gene and the only gene exhibiting significant adjusted p-values through multiple testing." (PMID 39455841, 2024).
tumor (continued). "The positive prognostic role of cytotoxic T cells remained statistically significant in a multivariable analysis including gender, age, localisation, tumour stage, BRAF mutation, KRAS mutation, and MSI status." (PMID 38040818, 2024). "It has been suggested that TEADs are mediators of the EGFR/RAS/RAF/MAPK pathway and play a crucial role in tumor progression and drug resistance in NSCLC with EGFR, KRAS, or BRAF mutation." (PMID 38499647, 2024). "KRAS was mutated in 88% and 74% of the tumor and blood samples, respectively, with high mutation abundance (MAF ≥ 30% and ≥ 5% in tumor and ctDNA samples, respectively) observed in 35% and 37% of the samples." (PMID 38378604, 2024). "IBI351, a synthetic compound, exerts its anti-tumor effects by specifically, covalently, and irreversibly modifying the 12th cysteine residue of KRAS G12C." (PMID 39433508, 2024). "Similar to other tumor cells, tumor cells driven by the KRAS gene display high levels of glycolytic activity, thereby enhancing glutamine anabolism." (PMID 38172980, 2024). "(2023) found that integrating immune checkpoint inhibitors with therapies targeting the KRAS pathway significantly enhanced immune response in pancreatic cancer models, reducing tumor progression and extending survival compared to single-agent treatments." (PMID 39539544, 2024). "Due to its effects on tumor immunity, it offers the potential for combining KRAS-G12C inhibitors with ICIs in subsequent treatments." (PMID 39802954, 2024). "The mutant-activated KRAS promotes tumor proliferation, metastasis, and invasion by stimulating multiple signaling routing pathways, such as the RAF-MEK-ERK signaling pathway, PI3K-AKT signaling pathway, and other signaling pathways." (PMID 38338834, 2024). "In summary, our work offers insights into how KRASG12V degradation influences both tumor progression and the immune response, underscoring the use of degraders as a potent strategy for targeting KRAS-mutant cancers." (PMID 39718828, 2024). "The tumor tissue samples of transgenic KrasG12D mice observed a significant expression of PEG3 as a downstream target of KRAS/ERK/MTOR-driven HCC." (PMID 39056802, 2024). "We propose that KRASG12C relies more on KRAS signaling through the MAPK arm to increase oncogenic potential and promote tumor growth rendering advanced KRASG12C tumors more susceptible to MAPK inhibition compared to KRASG12D tumors." (PMID 39533328, 2024). "In vivo, co-treatment with β-elemene and cetuximab inhibited KRAS-mutant tumor growth and lymph node metastases." (PMID 39125664, 2024). "For a given specimen, pathogenic variants of BRAF, EGFR, KRAS, and NRAS were identified and the determined VAFs were correlated with the corresponding tissue tumor cellularity." (PMID 38397405, 2024).
tumor (continued). "Recent reports have shown that changes in KRAS gene dosage alter the clonal evolution of tumours and change the metastatic incidence in KRAS mutant cancers." (PMID 38168062, 2024). "Using multiple KRAS-driven human LUAD cell lines, our work demonstrates that STK11 loss results in altered tumor-intrinsic cytokine expression, including but not limited to IL-6, CXCL8 and CXCL2." (PMID 37968341, 2024). "Here, we observed a direct correlation between FTH1 expression and cell viability and clonogenicity in KRAS-mutant PDAC cell lines as well as with in vivo tumor growth through the control of proline metabolism." (PMID 39294443, 2024). "This outcome mimics the tumor-suppressive effects observed with ODC overexpression in KRAS-mutant CRC cells." (PMID 39795950, 2024). "Among which is the use of natural chalcones that are known to exhibit anti-tumor activities in KRAS mutant CRC subtypes treatment regimens." (PMID 38463818, 2024). "The induced genetic deletion of mutant KRAS in the murine NSCLC tumor model Kras+/FSFG12Vlox;Trp53F/F;Rosa26-CreERT2KI/KI;Tg.hUBC-CreERT2+/T caused rapid tumor regressions." (PMID 38668053, 2024). "GC is characterized by both KRAS gene amplification and mutation but only few studies have been focused on the role of the different KRAS mutants in this tumour context." (PMID 38261067, 2024). "MiR-217 has been shown to inhibit in vitro tumor cell growth, and it acts as a potential tumor suppressor by influencing the Akt/KRAS signaling pathway." (PMID 38790924, 2024). "Preclinical investigation of opnurasib (JDQ443) showed potent and selective anti-tumor activity in KRAS G12C cell lines and comparable efficacy to sotorasib." (PMID 39337530, 2024). "KRAS mutations, which occur in over 90% of PDAC cases, drive oncogenic signaling pathways that promote tumor growth and survival." (PMID 39001391, 2024). "KAC markers were high in tumour regions and in TANs with reactive pneumocytes, and they spatially overlapped with the KRAS signature." (PMID 38418883, 2024). "Based on 2022 guidelines from the American Society of Clinical Oncology, the decision to initiate anti-EGFR treatment should be guided by the primary tumor location and testing for BRAF and RAS (KRAS and NRAS) mutations and deficient mismatch repair or MSI2." (PMID 38347302, 2024). "It has been reported in the literature that KRAS mutations were associated with CRC metastasis, NRAS promotes the colonization of the lungs by various tumor types in mouse models." (PMID 39507527, 2024). "Here, we show that tumor-mediated AICD can be exploited by oncogenic KRAS to dictate the formation of an immune-suppressive tumor microenvironment." (PMID 38216551, 2024). "Innate and acquired resistance mechanisms to KRAS inhibitors have already been documented and our understanding of the pleiotropic effects of oncogenic KRAS on the tumor microenvironment has evolved." (PMID 38576709, 2024). "CMS3 tumours are characterised by a higher CIMP status and high KRAS-mutation rate, while CMS4 tumours are characterised by a distal location, CIMP negativity, and are often microsatellite stable (MSS)." (PMID 39613865, 2024). "An in vitro and in vivo study showed that sustained activation of FAK in KRAS G12C inhibition led to KRAS G12C resistance, and the combination of a FAK inhibitor and a KRAS G12C inhibitor showed a synergistic anti-tumor effect in KRAS G12C-mutated xenografts." (PMID 38756650, 2024).
tumor (continued). "These circRNA‐expressing genes were significantly enriched in tumour‐related biological hallmarks, such as ‘Mitotic spindle’, ‘Apoptosis’, ‘Heme metabolism’, ‘KRAS signalling’, and ‘Angiogenesis’." (PMID 39428382, 2024). "Both in cell line- and patient-derived xenograft models, combining a ULK1/2 inhibitor and a KRAS G12C inhibitor rendered higher efficacy in tumor control." (PMID 38756650, 2024). "In essence, TGF-β drives SMAD4 signaling more effectively to protect tumor growth when KRAS is strongly inhibited." (PMID 38167055, 2024). "Among the six cases diagnosed at oncological stage IV, only one tumor exhibited a wildtype status of the KRAS gene." (PMID 38786321, 2024). "Ablation of mutant KRAS in a PDAC mouse model led to tumor regression followed by relapse facilitated by a fraction of surviving tumor cells with higher dependency on OXPHOS." (PMID 39363341, 2024). "Erastin, the first ferroptosis activator identified in 2003, exhibits significant lethality in human tumor cells carrying mutations in the HRAS, KRAS, and BRAF oncogenes." (PMID 38304870, 2024). "We conducted a prospective project to detect circulating tumor DNA (ctDNA) in patients with KRAS G12C, advanced NSCLC." (PMID 40027319, 2024). "To analyze the level of DHX15 in patient samples, we performed IHC on tumor tissues of patients with CRC that harbor KRAS p.G12D, p.G13D mutations, and KRAS WT allele." (PMID 38402201, 2024). "Another way to enhance the efficacy of KRAS G12C inhibition is to combine it with other agents with anti-tumor efficacy, such as immunotherapy and chemotherapy." (PMID 38756650, 2024). "From PDXs, we have been able to derive primary cell lines that maintain the KRAS alterations observed in the primary tumour." (PMID 38261067, 2024). "Combination of SOS1 and MEK inhibitors increase T cell infiltration while blunting pro-immune myeloid cell maturation and highlights the need for combining KRAS cancer-targeted therapy with myeloid activation to enhance and prolong anti-tumor effects." (PMID 38727236, 2024). "Phase I and II studies have shown that despite sustained anti-tumor activity, the objective response rate to KRAS G12C inhibition oscillates widely according to the primary tumor site, ranging from 30% in bronchial cancers to 7% in colorectal cancers." (PMID 39337479, 2024). "Geneset enrichment analysis (GSEA), identified key oncogenic programmes associated with KRAS signalling, MEK and AKT were enriched in villin-creERT2 Krasfl/G12D tumours." (PMID 38168062, 2024). "Both wild‐type and mutant KRAS groups showed separate clustering between patient tumor and PDMC based on ATAC‐seq." (PMID 38380561, 2024). "We defined enrichment as either a > 20% increase (tumor epithelium) or > 20% decrease (tumor stroma) in KRAS VAF compared to the bulk tumor tissue sample of the same patient." (PMID 38291365, 2024). "Alongside this, oncogenic KRAS also changes tumor metabolism to support quick proliferation and survival by increasing glucose uptake, enhancing glycolysis, and reprogramming lipid metabolism." (PMID 39061234, 2024).